MEG3 (maternally expressed 3)
Diseases named in the same sentence as MEG3 in open-access papers (continued):
Sharing a sentence is not in itself a finding about the gene and the disease.
glioma (continued). "Long non-coding RNAs (lncRNAs) such as MEG3 and CRNDE are also dysregulated in glioma tissues and may be associated with the stemness of glioma cells." (PMID 25191339, 2014). "MEG3 by suppression of autophagy could enhance cisplatin resistance in glioma." (PMID 34178658, 2021). "Therefore, further research is needed to verify the role of MEG3 in gliomas." (PMID 34220951, 2021). "Therefore, we conjectured that MEG3 may regulate certain intermediate to affect SMARCB1 in glioma cells." (PMID 32420340, 2020). "However, the roles of lncRNA MEG3 in glioma development and its molecular mechanisms remain unclear." (PMID 32420340, 2020). "However, the expression levels of Neat1, Mir142hg, Pvt1, Mir17hg, SNHG12 and Meg3 showed opposite trends, which may correlate with the distinct inflammatory profiles and immunophenotypes of the different glioma models analyzed." (PMID 40527978, 2025). "After analyzing the existing literature, we can state that the most reliable data seem to be related to the action of certain lncRNAs in gliomas, such as HOTAIR, NEAT1, MEG3, and MALAT1." (PMID 41149459, 2025). "Conversely, lncRNAs such as MEG3 and GAS5 have shown tumor-suppressive effects by inhibiting glioma cell growth and inducing apoptosis in adults." (PMID 37444408, 2023). "MEG3 negatively regulated cell proliferation by suppressing miR-19a, which in turn targeted PTEN in glioma cells." (PMID 36851033, 2023). "U87MG glioma cells and patient derived OLG cells showed that when MEG3 is post‐transcriptionally suppressed cell proliferation, and migration in glioma cells are reduced and chemosensitivity to the 5FU drug is achieved." (PMID 37525401, 2023). "MEG3 silenced and overexpressed in non‐cancerous HUVEC cells and U87MG glioma cells were compared to untreated control cells." (PMID 37525401, 2023). "Therefore, MEG3 may have therapeutic potential for gliomas in gene therapy." (PMID 35860793, 2022). "Meanwhile, by sponging miR-19a, MEG3 enhanced PTEN expression, thereby suppressing glioma cell migration and invasion potentials." (PMID 36551518, 2022). "DNMT1 expression is inversely correlated with the MEG3 transcript, supporting DNMT1’s involvement in MEG3 dysregulation in gliomas." (PMID 34316694, 2021). "MEG3 induces autophagy by upregulation of sirtuin 7 and inhibition on the PI3K/AKT/mTOR pathway in glioma cells." (PMID 33602903, 2021). "Collectively, lncRNA MEG3 decreased the phosphorylation levels of PI3K/AKT/mTOR pathways by enhancing Sirt7 and finally activates autophagy and improves the prognosis of glioma." (PMID 33029125, 2020). "Here, miR-6088 silence partially reversed MEG3 knockdown mediated repression of migration and invasion, and even EMT process of glioma cells." (PMID 32420340, 2020). "Altogether, the potential mechanism herein is that MEG3 negatively targets miR-6088 to regulate SMARCB, thus mediating the proliferation and migration of glioma cells." (PMID 32420340, 2020). "For example, MEG3 promotes autophagy and inhibits proliferation and migration of glioma cells, and HOXA10‐AS promotes the growth and survival of glioma cells." (PMID 32892482, 2020). "In this regard, we further reasoned that MEG3 mediates miR-6088, which in turn regulates SMARCB1 in glioma cells." (PMID 32420340, 2020). "The cellular expression of MEG3 was reported to be regulated by DNA methyltransferase (DNMT) 1 in lung cancer cells and in glioma cells, as well as by both DNMT1 and 3b in hepatocellular cancer cells." (PMID 30818784, 2019).
glioma (continued). "We observed moderate negative linear correlation (rs = −0.373, p = 0.005) between expression of miR-770 and MEG3, and positive correlation (rs = 0.291, p = 0.028) between expression of miR-124a and RNCR3 in all glioma samples." (PMID 29138748, 2017). "Among differentially expressed lncRNAs, we further validated seven lncRNAs (7SL, EGO-A, HOTAIR, JPX, MEG3, RNCR3, and ZFAS1) on a bigger cohort of glioma samples of different WHO malignancy grades and histopathological subtypes." (PMID 29138748, 2017). "For example, we found human lincRNAs NAG7, MEG3, PCAT1, CASC2 and LINC00032, which were involved in nasopharyngeal carcinoma, glioma and bladder cancer, prostate cancer, endometrial cancer and melanoma." (PMID 25075616, 2014). "Thus, the MEG3/DNMT1 axis significantly contributes to human glioma pathogenesis, highlighting its potential as a novel therapeutic target in glioma treatment." (PMID 40387409, 2025). "MEG3 inhibition improved the chemosensitivity of glioma cells to 5‐fluorouracil (5FU) but not to navitoclax." (PMID 37525401, 2023). "Although the 5FU treatment had a minor negative effect on U87MG glioma cell viability in nontransfected control cells expressing normal levels of MEG3, did not significantly inhibit cell proliferation." (PMID 37525401, 2023). "MEG3 silencing in glioma cells switched the cell populations into early apoptotic and late apoptotic cell phenotypes, whereas the control and MEG3 overexpressed cells showed no significant apoptotic induction." (PMID 37525401, 2023). "The Nvtx treatment did not significantly inhibit the viability of glioma cells expressing MEG3 at normal levels." (PMID 37525401, 2023). "However, MEG3 overexpression significantly promoted cell proliferation within 24 and 48 h of treatment in U87MG glioma cells." (PMID 37525401, 2023). "Only one expressing vector was used for MEG3; therefore, it was not able to investigate the dose-inhibition response of the gene in glioma." (PMID 35860793, 2022). "A team from Jilin University reported that MEG3 inhibited the proliferation and migration of U251 cells by positive regulation of sirtuin 7 (Sirt7) and participates in the suppression of the PI3K/AKT/mTOR axis in glioma." (PMID 36544907, 2022). "Second to MEG3, the anti-tumoral effects of GAS5 are well investigated in glioma." (PMID 34322395, 2021). "Additionally, MEG3 acted as a ceRNA to miR-19a, which repressed PTEN (phosphatase and tensin homolog) expression, leading to glioma cell proliferation, migration and invasion." (PMID 34316694, 2021). "In brain and CNS cancers, six studies reported the downregulation of MEG3, whereas no study reported its upregulation." (PMID 34220951, 2021). "In this work, we found downregulated MEG3 and SMARCB1 in glioma cells, but no direct interaction of MEG3 and SMARCB1 was identified." (PMID 32420340, 2020). "The lncRNA maternally expressed 3 (MEG3) is significantly downregulated in glioma tissues and cell lines, and its over expression can significantly inhibit cell proliferation and promote the apoptosis and autophagy of glioma cells." (PMID 33149738, 2020).
glioma (continued). "Indeed, it has been shown that low expression of MEG3 correlates with short survival in GBM patients and, if reintroduced in glioma stem cells (GSCs), it inhibits cell proliferation and in vivo tumor growth." (PMID 33066171, 2020). "MEG3 and SMARCB1 expressions were downregulated in glioma cells." (PMID 32420340, 2020). "However, in their study, MEG3 expression was significantly downregulated in various brain cancers and also in glioma tissue, which negatively correlated with WHO grade in glioma patients." (PMID 32650527, 2020). "Therefore, we aim to explore the possible role of MEG3 and SMARCB1 in glioma cells and to further clarify the mechanism herein." (PMID 32420340, 2020). "Taken together, MEG3 inhibits cell migration and EMT of glioma cells." (PMID 32420340, 2020). "Consistent with its tumor-suppressor role, the reduction of MEG3 expression has been observed in NFPA as well as other types of tumors such as hepatocellular carcinoma, non-small-cell lung cancer, glioma and meningioma." (PMID 30504132, 2019). "Studies have shown that TUG1 and MEG3 expression levels are reduced in human glioma tissues, with TUG1 promoting cell apoptosis and suppressing proliferation, migration, and invasion, while GAS5 was identified as a suppressor that enhances glioma therapy efficacy by directly targeting miR-222." (PMID 40004468, 2025). "Hence, we can propose that MEG3 activity is important in the chemosensitivity of glioma cells to 5FU but not to Nvtx." (PMID 37525401, 2023). "Nonetheless, the molecular mechanism of MEG3 in glioma is still not clear." (PMID 36544907, 2022). "lncRNA MEG3 was lowly expressed in glioma cells as compared to noncancer cells." (PMID 35860793, 2022). "Further, a study has found that the PIWIL1/piRNA-DQ593109 (piR-DQ593109) complex is a major regulator of blood-tumor barrier (BTB) permeability in glioma through the MEG3/miR-330-5p/RUNX3 axis, and their inhibitions could enhance efficient delivery of anti-glioma drugs to glioma tissues." (PMID 36009578, 2022). "Although the role and prognostic value of the dysregulation of MEG3 in gliomas has not yet been fully evaluated, the current findings suggest that MEG3 may regulate tumor progression via immune-based mechanisms." (PMID 34220951, 2021). "However, to the best of our knowledge, the immune-specific functions of MEG3 expression in gliomas have not yet been evaluated." (PMID 34220951, 2021). "Furthermore, the effects of MEG3 gene expression were compared between non‐cancerous human umbilical vein endothelial cord (HUVEC) cells and U87MG glioblastoma cells either derived from ATCC or patients with different pathological grades and histopathological subtypes of glioma tumours." (PMID 37525401, 2023). "In the gliomas, colorectal neoplasia differentially expressed nonprotein coding (CRNDE) and LOC400043 were significantly upregulated, while maternally expressed gene 3 (MEG3) was significantly downregulated." (PMID 32650527, 2020).
breast cancer (86 papers, 2014 to 2025). A primary or metastatic malignant neoplasm involving the breast. "In gene–miRNA–lncRNA functional module 1, lncRNA MEG3 contributes to the development of cardiac fibrosis while the expression of miRNA hsa-mir-100 is associated with fibroblasts in breast cancer." (PMID 38088228, 2024). "The dysregulation of hsa-let-7b is associated with breast cancer and MEG3 acts as a tumor suppressor in breast cancer development and progression." (PMID 38088228, 2024). "This indicated that MEG3 polymorphism has the potential as a prognostic marker for breast cancer individuals." (PMID 36817434, 2023). "Aside from their expression patterns their sequence polymorphisms can also provide valuable insights such as those of MEG3 in breast cancer which have been associated with therapeutic efficacy, therefore making them valuable predictive markers for patients." (PMID 35788171, 2022). "It was reported that MEG3 overexpression caused inhibition of proliferation and invasion of breast cancer cells." (PMID 35328609, 2022). "The purpose of the study is to investigate the effect of MEG3 SNP (rs7158663 G/A) and its association with breast cancer risk." (PMID 34421993, 2021). "The study aims to investigate the effect of MEG3 SNP (rs7158663 G/A) and its association with breast cancer risk in the Egyptian population." (PMID 34421993, 2021). "The current study results suggest that the MEG3 gene rs7158663 polymorphism is associated with susceptibility to a variety of cancers, such as breast cancer, gastric cancer and CRC." (PMID 34956908, 2021). "Differences in allele distribution and genotype frequency of MEG3 gene single nucleotide polymorphism (SNP) rs7158663 G/A between control, fibroadenoma, and Breast cancer groups." (PMID 34421993, 2021). "For example, MEG3 gene rs3087918 was associated with a decreased risk of breast cancer in a Chinese population." (PMID 34956908, 2021). "This study is aimed to investigate the association between MEG3 polymorphisms (rs3087918, rs11160608 rs7158663) and breast cancer." (PMID 32669097, 2020). "The wild-type homozygous GG of MEG3 rs3087918 was associated with a decreased risk of breast cancer." (PMID 32669097, 2020). "Previous investigation indicated that several SNPs in MEG3 genes are associated with breast cancer susceptibility." (PMID 32669097, 2020). "This study is aimed to explore the association between three SNPs of MEG3 (rs3087918, rs7158663, rs11160608) and breast cancer." (PMID 32669097, 2020). "In this study, we genotyped three polymorphisms (rs3087918, rs11160608 rs7158663) in MEG3 gene based on 434 BC patients and 700 healthy controls, to explore their relationship with breast cancer." (PMID 32669097, 2020). "As far as we know, this is the first time to report the relationship between MEG3 lncRNA polymorphisms, efficacy and prognosis in locally advanced breast cancer patients who received neoadjuvant chemotherapy." (PMID 31488093, 2019). "The result indicates that MEG3 polymorphisms can be considered as the predictive and prognostic markers for the breast cancer patients." (PMID 31488093, 2019). "In conclusion, MEG3 rs10132552 was associated with the cisplatin-containing chemotherapy response in breast cancer patients, and MEG3 rs10132552 and rs941576 were associated with disease free survival." (PMID 31488093, 2019). "Recently, a number of lncRNAs were documented to be associated with TGFß signaling pathway, including MEG3 regulating the TGFB2 pathway in breast cancer." (PMID 30642353, 2019). "Our result indicated that the MEG3 polymorphism was also associated with cell growth in breast cancers." (PMID 31488093, 2019). "It was reported that some LncRNAs were tumor suppressor in breast cancer, such as growth arrest-specific 5, neuroblastoma associated transcript 1, and maternally expressed 3 (MEG3)." (PMID 31488093, 2019).
breast cancer (continued). "In conclusion, the current findings suggest that the MEG3 gene rs7158663 polymorphism may serve as a genetic marker for predicting the risk of cancers, such as breast cancer, gastric cancer and CRC." (PMID 34956908, 2021). "As a result, we hypothesize that rs7158663 is a regulatory SNP that controls MEG3 expression and contributes to breast cancer genetic susceptibility." (PMID 34421993, 2021). "In this study, we found MEG3 rs3087918 was associated with a decreased breast cancer risk." (PMID 32669097, 2020). "MEG3 rs3087918 was associated with a decreased risk of breast cancer." (PMID 32669097, 2020). "MEG3 haplotype TCG may increase the risk of breast cancer and it may owe to its effect on the structure and function of MEG3." (PMID 32669097, 2020). "In this study, we detected the SNPs of long chain non-coding RNA MEG3 and analyzed the relationships between the polymorphisms and clinicopathological features, neoadjuvant chemotherapy sensitivity, prognosis and the toxicities of breast cancer patients." (PMID 31488093, 2019). "Therefore, it is critical to elucidate the underlying mechanism upstream MEG3 to regulate breast cancer metastasis." (PMID 30386180, 2018). "More interestingly, MEG3 has been implicated into tumorigenesis and progression of breast cancer." (PMID 30386180, 2018). "Likewise, decreased expression levels of FGF14 antisense RNA 2 (FGF14‐AS2), X inactive specific transcript (XIST), BC040587, and MEG3 in breast cancer tissue and cell lines compared with corresponding normal control were associated with unfavorable survival in breast cancer." (PMID 36274054, 2023). "Moreover, SNP within the MEG3 intron may increase, among others, the susceptibility of breast cancer, oral squamous cell carcinoma, and type 1 diabetes." (PMID 34885213, 2021). "Additionally, the GG genotype of rs3087918 could influence the secondary structure of MEG3 and decrease the susceptibility to breast cancer risk in Chinese women." (PMID 34527584, 2021). "Next, extensive bioinformatic analyses on RNA-seq data from MCF7 with MEG3 overexpression and MCF10A with MEG3 depletion suggested CXCR4 as the major target downstream MEG3 that mediated breast cancer cell migration." (PMID 40548301, 2025). "Previous reports suggested that MEG3 was a nuclear lncRNA with decreased expression in many different malignancies including breast cancer." (PMID 40548301, 2025). "As compared to the normal tissues, the expression level of MEG3 was significantly downregulated in breast cancer (p = 1.17e-40)." (PMID 40548301, 2025). "Altogether, these results indicated that CXCR4 was the major target downstream MEG3 and MEG3 regulated breast cancer cell migration via CXCR4." (PMID 40548301, 2025). "Decreased expression of lncRNA MEG3 has been reported in many malignancies, including breast cancer." (PMID 40548301, 2025). "The DNA methyltransferase DNMT1 induces hypermethylation of the promoter of MEG3 and inhibits its expression, which then promotes the growth of breast cancer cells through the regulation of the miR-494-3p/OTUD4 axis." (PMID 41050073, 2025). "Bioinformatic analysis on RNA-seq data from MCF7 with MEG3 overexpression and MCF10A with MEG3 depletion led to the identification of CXCR4 as the major downstream mediator negatively regulated by MEG3 that facilitated breast cancer cell migration." (PMID 40548301, 2025). "Next, we performed clone formation and MTT assay to determine the impact of MEG3 on breast cancer cell proliferation." (PMID 40548301, 2025). "We provided further evidence to show that cell migration was the phenotype with close correlation to MEG3 expression level in breast cancer cell lines." (PMID 40548301, 2025). "Overall, our study pinpoints the importance of MEG3/CTCF-CXCR4 axis in regulating migration of breast cancer cells and provides novel insight into the mechanism of lncRNA MEG3 in cancer development." (PMID 40548301, 2025).